KRAS (KRas proto-oncogene, GTPase)
Diseases named in the same sentence as KRAS in open-access papers (continued):
Sharing a sentence is not in itself a finding about the gene and the disease.
tumor (continued). "Finally, GEMM studies support a potential tumor suppressor function of the KRAS WT allele." (PMID 40829181, 2025). "However, it is rarely reported that tumor organoids naturally expressing KRAS mutations and specific HLA are used to investigate the recognition and killing of tumor target cells by T cells engineered with TCRs targeting KRAS mutations." (PMID 39846249, 2025). "Moreover, KRAS mutations play a role in shaping the TME early in tumor development." (PMID 40485603, 2025). "Furthermore, targetable mutations in KRAS or PIK3CA may affect tumor recurrence and survival in patients with BTCs." (PMID 41301905, 2025). "Oncogenic KRAS mutations engage in various metabolism pathways in tumors, including lipometabolism, glycometabolism, amino acid metabolism, and nucleotide metabolism, to meet the high biosynthetic demands of proliferating tumor cells and accelerate their growth." (PMID 41184283, 2025). "Indeed, alterations in KEAP1 and/or STK11, which are especially frequent in KRAS-mutated tumours, promote an immunosuppressive tumour microenvironment, enriched in suppressive myeloid cells and depleted in CD8+ cytotoxic T cells, but with relative sparing of CD4+ effector T cells." (PMID 40849356, 2025). "The findings suggest that targeting KRAS expression, particularly through G4 ligands, holds potential for modulating tumor immunity, but further exploration into the specific mechanisms by which these ligands could influence the immune responses associated with KRAS mutations is needed." (PMID 40333779, 2025). "Third, KRAS mutations are driver “hotspot” mutations that play a critical role in tumorigenesis and are likely to be clonally expressed in all tumor cells present in a patient with cancer, and thus targeting KRAS mutations may overcome tumor antigen heterogeneity." (PMID 39846249, 2025). "Polymerase Chain Reaction (PCR—EasyPGX ready KRAS, Diatech Pharmacogenetics, Jesi, Italy) revealed a KRAS c.34G > T p.G12C mutation while immunohistochemistry (IHC—antibody 22C3 pharmDx, Dako, Santa Clara) for Programmed Death Ligand 1 (PD-L1) tested positive in 5% of tumor cells." (PMID 40110764, 2025). "Generally speaking, the presented ML pipeline could be deployed for other classification tasks (e.g., classification of EGFR or ALK mutation instead of KRAS, or tumor phenotyping as originally envisioned for radiomics), and besides radiomic features, any tabular dataset could be used or added." (PMID 39860023, 2025). "Consequently, the observed enrichment of KRAS mutations in samples with higher tumor purity may reflect a greater proportion of tumor cells capable of harboring this driver mutation." (PMID 40981070, 2025). "Future research should further elucidate: 1) the signal regulation network of Hes1 in different tumor microenvironment; 2) the molecular switching mechanism underlying its stage-dependent role; and 3) the synergistic mode of action with driver genes such as KRAS." (PMID 40755759, 2025).
tumor (continued). "Furthermore, the KRAS c.35G>T (p.Gly12Val) mutation was associated with a poor immune response within the tumor microenvironment, characterized by lower tumor-infiltrating lymphocytes and higher tumor–stromal percentage, which exacerbates the aggressive nature of KRAS c.35G>T (p.Gly12Val) in mCRC." (PMID 40075837, 2025). "Specifically, common driver mutations, such as EGFR and KRAS mutations, have been found to be predominantly clonal, while failure to identify a driver clone may indicate a tumor composed of multiple subclones of different mutational origins without a dominant driver clone." (PMID 41345846, 2025). "Furthermore, KRAS mutations contribute to tumor initiation and progression." (PMID 39941797, 2025). "In addition, the levels of tumor-derived mutant KRAS DNA were highest in association with large EVs and sEVs early and with sEVs and soluble proteins late in disease progression, indicating that sEVs were the most enriched in tumor-derived DNA throughout disease progression." (PMID 39402599, 2024). "Moreover, KRAS mutations are associated with tumor immune evasive phenotype." (PMID 38397927, 2024). "Alternatively, if enough tumor tissue is available and morphology has an atypical phenotype (e.g., pleomorphic or giant cell-rich tumors), KRAS mutation analysis can be performed, as independently of their morphology, the vast majority of PC harbor KRAS mutations." (PMID 39632706, 2024). "Additionally, we could not find any association between RICTOR amplification and any other genetic drivers (ALK translocation and KRAS mutation status were available in 286 and 15 patients, respectively) or tumor mutational burden." (PMID 38706776, 2024). "Interestingly, KRAS-mutated tumours may demonstrate differing biology and therapeutic vulnerabilities depending on the particular mutation subtype, as well as co-occurring genetic alterations." (PMID 39749035, 2024). "Moreover, the impact of each KRAS mutation appears notably contingent on the tumor type." (PMID 39164274, 2024). "Additionally, 4% of patients with PDAC had multiple concurrent mutations of the KRAS gene, which could be further seen in different cells of the same tumor." (PMID 38893220, 2024). "Having a buffer for RAC1 activity could provide advantages for tumours, where mutations in KRAS will drive high activation of RAC1, which might be detrimental to cell survival due to enhanced reactive oxygen species production and enhanced downstream signalling." (PMID 38712822, 2024). "In this sense, it has been reported that variants in the 3′UTR region of the KRAS gene could modify the miRNA-binding sites that could regulate it, and that some of these variants have also been associated with different types of neoplasms." (PMID 39057123, 2024). "However, in multivariate analysis, the presence of a G12D and/or G12C mutation in the tumor was the only factor significantly associated with a lower PFS when compared with other KRAS status (i.e., WT, G12R and G12V mutations) (HR 1.792, 95% CI 1.061–3.028, p = 0.029)." (PMID 39456638, 2024).
tumor (continued). "Given that tumors are heterogenous, particularly when metastasized and subjected to several lines of drug pressure, tumor cells harboring specific oncogenic mutations (i.e. KRAS) may confer EGFR-targeted mAb resistance to otherwise treatment-sensitive WT cells via paracrine signaling." (PMID 40727266, 2024). "Therefore, we tested a hypothesis that clinical and tumor characteristics of KRAS c.34G>T (p.G12C)‐mutated tumors might differ from those of other KRAS‐mutated tumors and KRAS‐wild‐type tumors." (PMID 39039804, 2024). "Moreover, KRAS mutations are considered to be early events in tumor formation." (PMID 38255325, 2024). "The presence of KRAS G12C mutation may have exacerbated tumor invasiveness." (PMID 39777351, 2024). "Additionally, the US organoid has a KRAS G12A mutation and a high tumor mutational burden, which may contribute to the observed heterogeneity in US organoid growth through dysregulation of cell proliferation." (PMID 39093897, 2024). "This study would be strengthened by availability of genetic analysis of tumours (such as microsatellite instability, KRAS and BRAF mutations), or specific details regarding adjuvant chemotherapy use, side-effect profile and completion which may be potential confounders." (PMID 38637820, 2024). "Furthermore, these TCR-transduced peripheral blood lymphocytes (PBLs) could recognize plenty of HLA-A*11:01(+) tumor cell lines expressing the KRAS G12V and G12D mutations." (PMID 36761724, 2023). "However, IL10 increase in HES1 (−) tumors may implicate the complex tumor microenvironment remodeled by KRAS mutation and/or HES1-loss." (PMID 37749297, 2023). "Similarly to what occurred in the xenograft model, combined KRAS G12C and eIF4A inhibitors also caused potent and durable tumor regression in a KRAS G12C–mutant patient-derived xenograft (PDX) model (DFCI-730), with tumors regressing up to 85%–90% in response to the drug combination." (PMID 37384411, 2023). "Similarly, KRAS mutations confer the constitutive activation of this oncogene, stimulating cell proliferation, inducing autophagy, suppressing apoptosis, altering cell metabolism, changing cell motility and invasion, and modulating the tumor microenvironment." (PMID 37298928, 2023). "In cancer cells, KRAS-induced loss of cilia establishes asymmetry versus ciliated mesenchymal cells in the tumor microenvironment, affecting ability to respond to Hh, which selectively activates CAFs to produce the extracellular matrix and soluble factors required to support tumor growth." (PMID 37452870, 2023). "Therefore, KRAS mutations are broadly recognized as promising targets for tumor therapy." (PMID 37828002, 2023). "Intervention of FSP1 and expression in the early stage of atypical adenomatoid hyperplasia (AAH) to adenocarcinoma in situ (AIS) or to micro-infiltrating adenocarcinoma (MIA), and thus intervention in ferroptosis of tumor initiation, may be a novel therapeutic direction for KRAS-mutated LUAD." (PMID 37834062, 2023). "Importantly, multiple concurrent KRAS mutations were detected in approximately 4% of PDACs, and, interestingly, these different KRAS mutations could be presented in different cells of the same tumor." (PMID 36761724, 2023). "In addition, we found cytotoxic CD8+ T‐cell tumor infiltrate was unlikely to correlate with the KRAS mutation type, which suggests that the findings of tumor immune evasion might be a general feature of KRAS mutant CRC." (PMID 36599679, 2023). "Thus, RADIL might be playing different roles in the migration of tumour cells that express specific KRAS point mutations." (PMID 37627169, 2023). "Thus, inhibition of KRAS or autophagy could be a promising therapeutic strategy for tumor cells harboring KRAS mutations." (PMID 35883626, 2022).
tumor (continued). "Recent robust evidence suggests that both NKs and CD8+ T cells (tumor-infiltrating lymphocytes (TILs)) are associated with better prognosis and are able to “sculpture” the neoplastic population by eliminating some neoplastic clones, including those carrying KRAS mutations." (PMID 35936004, 2022). "However, the one-size-fits-all approach in looking for suitable PDAC biomarkers has been paralleled by approaches looking for multiple alterations, as done by targeting KRAS (and other) mutations in circulating tumor DNA coupled with the assessment of thresholded proteins." (PMID 36497278, 2022). "Moreover, mutant KRAS may also promote tumor development and immune evasion via causing an immunosuppressive microenvironment." (PMID 36172359, 2022). "KRAS mutations play a vital role in controlling tumor metabolism, e.g., by stimulating glucose uptake, and an increased need for energy and elevated aerobic glycolysis are closely associated with chemoresistance, tumor progression, and metastasis of malignant tumors." (PMID 35888776, 2022). "Thus, we propose that G12V KRAS variant may contribute to the worst prognosis in ICC by mediating tumor lymphatic metastasis." (PMID 34730772, 2022). "Similarly, KRAS mutation was significantly associated with tumour differentiation (P < 0.001)." (PMID 36582783, 2022). "In addition, we have observed that the KRAS mutational status and the tumor grade of differentiation have a relationship with survival in this type of patients and that these factors attain a prognostic information that is independent and complementary to that provided by the PCI." (PMID 36013160, 2022). "Moreover, VEGF receptor-mediated angiogenesis has the RAF/MEK pathway as its regulatory hub, suggesting how different KRAS mutations may be involved more or less deeply in the development of peri-tumor neo vessels." (PMID 36523988, 2022). "Finally, a phase II clinical study specified 47% tumor shrinkage in the KRAS-harbored mutation." (PMID 35409064, 2022). "Therefore, even if the tumour specimens are sampled from the primary site, there is still low cancer cell abundance in the specimens, and some KRAS mutations may be missed." (PMID 36582783, 2022). "In cancer cells, KRAS mutations confer the constitutive activation of this oncogene, stimulating cell proliferation, inducing autophagy, suppressing apoptosis, altering cell metabolism, changing cell motility and invasion and modulating the tumor microenvironment." (PMID 35883626, 2022). "This study aimed to investigate the presence of KRAS mutations by ultra-sensitive droplet digital PCR in the resection and venous margins of R0 resected tumour samples, identifying rare microscopically undetectable tumour cells in tissue areas, declared healthy by the pathologist." (PMID 35194118, 2022). "KRAS is an oncogene whose activation causes a series of changes in metabolic pathways and stimulation of different intracellular growth factors and transcription factors, which lead to the stimulation of tumour cell proliferation that favours invasion, migration, and metastatic dissemination." (PMID 35454771, 2022). "However, there are undoubtedly other indirect mechanisms driving RAS oncogenic activity in KRAS wt tumours, such as epigenetic regulation, inter-exonic variants, influence of the tumour microenvironment and growth factor expression, negative feedback loop regulation, metabolic regulation or others." (PMID 36163168, 2022).
tumor (continued). "We conclude that PCI should continue as the as the most useful prognostic indicator in order to assess prognostic estimations, therapeutic and surgical decisions, but tumor grade and KRAS mutational status may help in the treatment decision process by providing complementary information." (PMID 36013160, 2022). "Furthermore, KRAS is associated with tumor formation and malignant transformation." (PMID 35686701, 2022). "However, as the mutation status of tumor tissue is unknown, this study cannot distinguish between the detection of ctDNA as a prognostic factor or the known association between KRAS mutated tumors and prognosis." (PMID 35565347, 2022). "In a KRAS-induced pancreas cell orthotopic implantation model, Rip3 deletion (KrasG12D/+; Rip−/−) leads to an increased number of T cells and decreased number of tumor-associated macrophages (TAM), indicating that necroptosis-induced CXCL1 signaling promotes immunosuppression." (PMID 35159011, 2022). "In this study, the mutant KRAS detection rate in patients with localizedPDAC after surgical resection dropped from 66.7% before surgery to 5% after surgery,indicating that EV-associated KRAS mutations could serve as biomarkers for real-timemonitoring of therapy response and tumor burden." (PMID 39703905, 2021). "Therefore, tumor-intrinsic inflammatory signaling not only overcomes the senescence barrier that hinders transformation of pre-malignant, KRAS-mutated cells, but is also a critical mechanism through which KRAS-mutant cells subvert the external stromal and immune cells." (PMID 34771644, 2021). "Moreover, oncogenic KRAS interacts with other mutated oncogenes and tumor suppressor genes, inducing a pro-inflammatory immunosuppressive stroma, which contributes to immune evasion and tumor progression." (PMID 34064352, 2021). "Notably, the only codon 12 KRAS mutation in incident CRCs was detected in a stage I tumor." (PMID 34206061, 2021). "In addition, tumor cells harboring KRAS mutations have shown NPM1 expression dependency." (PMID 34781949, 2021). "The null hypothesis tested was that, assuming the cancer would acquire a KRAS mutation and one of the common alleles (found in >3% of the tumor samples for a given cancer) was sufficient, the frequency of the KRAS alleles would be determined by the mutational processes alone." (PMID 33753749, 2021). "Interestingly, the use of AMG 510 (a KRAS G12C inhibitor) in pre-clinical models showed a prominent effect on anti-tumor immunity, causing an increase of CD3+, CD8+ T, and dendritic cell infiltration and inducing upregulation of MHC class I complex on tumor cells." (PMID 34072037, 2021).